DSG3 (desmoglein 3)
Diseases named in the same sentence as DSG3 in open-access papers (continued):
Sharing a sentence is not in itself a finding about the gene and the disease.
pemphigus vulgaris (continued). "Anti-Desmoglein 3 (Dsg3) IgG antibodies from patients with pemphigus vulgaris (PV) exhibit significantly elevated levels of Fab glycosylation." (PMID 41301426, 2025). "The researchers engineered CAAR T cells for pemphigus vulgaris (PV), an autoimmune skin condition where autoreactive B cells target desmoglein 3 (Dsg3)." (PMID 40755780, 2025). "Together, KLF5 and histone deacetylase 3 are regulators of desmoglein 3 gene expression and intercellular adhesion and represent potential therapeutic targets in pemphigus vulgaris." (PMID 39271654, 2024). "CAAR T cell therapy is particularly relevant for diseases driven by well-defined autoantigens, such as muscle-specific tyrosine kinase (MuSK) in myasthenia gravis or desmoglein 3 (DSG3) in pemphigus vulgaris." (PMID 39697333, 2024). "In pemphigus vulgaris, Tregs play a pivotal role in controlling the activity of desmoglein-3-reactive lymphocytes, thereby preventing disease onset." (PMID 39796035, 2024). "Pemphigus vulgaris (PV) is an autoimmune disease characterized by IgG autoantibodies targeting desmoglein-3 (Dsg3), leading to blistering of mucous membranes and skin." (PMID 39416775, 2024). "Pemphigus vulgaris (PV) shows the production of anti-Dsg3 in the mucosal form, and anti-Dsg1 and 3 in the mucocutaneous form." (PMID 38851894, 2024). "In pemphigus vulgaris (PV), Dsg3-specific antibodies induce acantholysis in the basal and suprabasal layers of the mucous membranes, resulting in painful and slow-healing sores." (PMID 37174740, 2023). "Apart from that, in another desmosomal disease, pemphigus vulgaris (PV), an autoimmune condition caused by autoantibodies against DSG1 and/or DSG3, which leads to blister formation in skin and mucosa, p38MAPK is activated, which can be recapitulated in vitro." (PMID 36733457, 2023). "The mucosal-dominant variant of pemphigus vulgaris (MPV) is an autoimmune disease characterized by oral mucosal blistering and circulating pathogenic IgG antibodies against desmoglein 3 (Dsg3), resulting in life-threatening bullae and erosion formation." (PMID 37511259, 2023). "Desmoglein 3 (Dsg3) is a desmosomal cadherin mediating cell adhesion within desmosomes and is the antigen of the autoimmune blistering skin disease pemphigus vulgaris." (PMID 36602635, 2023). "Pemphigus vulgaris is a severe, socially significant autoimmune diseaseassociated with autoantibodies to the desmoglein 3 antigen." (PMID 37153513, 2023). "protein of desmosomes in stratified squamous epithelium, desmoglein 3 (Dsg3),play a key pathogenetic role in the development of pemphigus vulgaris." (PMID 37153513, 2023). "Monkey oesophagus provides a rich source of desmoglein proteins, particularly desmoglein-3 and is therefore the substrate of choice for the detection of pemphigus vulgaris antibodies." (PMID 38074463, 2023). "In an illustrative example, Stanley and colleagues followed up on an earlier study investigating B cells specific to the Dsg3 autoantigen in pemphigus vulgaris patients, interrogating the anti-Dsg3 autoantibodies in serum using Ig-Seq." (PMID 35178051, 2022). "In a murine model of pemphigus vulgaris CAAR T cells expressing the target autoantigen – i.e. desmoglein 3 – specifically and efficiently eliminated desmoglein 3-specific autoreactive B-cells." (PMID 35603210, 2022). "Pemphigus vulgaris (PV) is a life-threatening autoimmune blistering disease resulting from the formation of IgG autoantibodies directed against autoantigen desmoglein 3 (Dsg3) within the epidermis and mucous membranes." (PMID 36348826, 2022). "We studied the distribution and in vitro pathogenicity of anti-DSG3 IgG subclasses during the course of pemphigus vulgaris (PV)." (PMID 35371083, 2022). "Together, the autoantibodies against both desmoplakin and desmoglein 3 induce the different phenotypes of pemphigus vulgaris and PNP in the aspect of humoral immunity." (PMID 35911677, 2022).
pemphigus vulgaris (continued). "We also observed that most CD11c+ DN B cells were FcRL5+ cells in Dsg3-specific B cells from pemphigus vulgaris patients." (PMID 35983042, 2022). "In their study, single-cell repertoire analysis of circulating Dsg3-specific memory B cells from pemphigus vulgaris patients revealed that these cells were mostly class-switched and affinity-matured." (PMID 34068035, 2021). "In contrary, expression of antibodies against desmoglein 1 and desmoglein 3 is characteristic rather of pemphigus vulgaris (PV), pemphigus foliaceus (PF) and paraneoplastic pemphigus (PNP) but not PAMS." (PMID 33995340, 2021). "Serologically, the predominantly cutaneous presentation has circulating anti-Dsg1 and anti-Dsg3 autoantibodies, with a tendency to higher titers of anti-Dsg1 than anti-Dsg3, which implies a rare clinical phenotype of pemphigus vulgaris." (PMID 34006398, 2021). "DSG3 has been identified as an autoantigen in the skin disease pemphigus vulgaris and is also upregulated in several cancers, including squamous cell carcinoma, pancreatic ductal adenocarcinoma, and head and neck cancer." (PMID 33901011, 2021). "These important genes include DSG3 and ABCA12 where loss of function results in skin diseases such as pemphigus vulgaris and harlequin ichthyosis." (PMID 33542242, 2021). "Autoantibodies (autoAbs) against desmoglein-1 (DSG1) and desmoglein-3 (DSG3) have conventionally been studied and well accepted in the pathogenesis of pemphigus vulgaris (PV) and foliaceus (PF)." (PMID 32555697, 2020). "Desmoglein 3, the target antigen of pemphigus vulgaris, an IgG-mediated autoimmune blistering disease, was used in a HaloTag protein barcode assay to detect the anti-DSG3 antibody." (PMID 31752022, 2020). "For instance, the layer-specific nature of skin lesions in the autoimmune diseases pemphigus vulgaris and pemphigus foliaceus correspond to the layers in which the target antigen (i.e. Dsg3 versus Dsg1) is at its highest concentration." (PMID 31942240, 2019). "Antibody profiles of pemphigus vulgaris patients' IgG fractions as determined by ELISA for Dsg1 or Dsg3, respectively, and clinical phenotype." (PMID 31024527, 2019). "Pemphigus vulgaris and foliaceus are severe autoimmune blistering skin diseases with autoantibodies that are directed against the desmosomal cadherins, mainly desmoglein 3 (Dsg3) and Dsg1." (PMID 31447854, 2019). "DSG3 has been shown to be the self-antigen for autoantibodies in the pemphigus vulgaris (PV) disease and is known as PV antigen (PVA)." (PMID 30510564, 2018). "Primary human keratinocytes treated with pemphigus vulgaris (PV) IgG containing antibodies targeted to the adherens junction protein desmoglein 3 (Dsg3) exhibited reorganized Dsg3 at the membrane into projections perpendicular to the membrane plane." (PMID 29701678, 2018). "Desmoglein3 (DSG3) has been identified as one of the autoantigens in an autoimmune blistering skin disease called pemphigus vulgaris (PV)." (PMID 30510564, 2018). "All pemphigus vulgaris (PV) and pemphigus foliaceus (PF) IgG and AK23, a monoclonal mouse antibody against Dsg3, caused loss of cell cohesion, cytokeratin retraction and p38MAPK activation." (PMID 28620161, 2017). "Pemphigus vulgaris (PV) is an autoimmune disease characterized by the presence of IgG autoantibodies against desmoglein-3." (PMID 28321152, 2017). "DSG3 is also known as pemphigus vulgaris antigen (PVA) and is the calcium-binding, transmembrane glycoprotein component of desmosomes in vertebrate epithelial cells." (PMID 26700817, 2016). "Pemphigus vulgaris (PV) is a human autoimmune disease that is characterised by autoantibodies against Dsg3." (PMID 27346727, 2016). "Dsg3 has been identified as one of the autoantigens in the autoimmune blistering skin disease pemphigus vulgaris (PV)." (PMID 23326495, 2013). "In pemphigus vulgaris circulating IgG antibodies to Dsg3 are present either alone or in combination with antibodies to Dsg1." (PMID 24278779, 2013).
pemphigus vulgaris (continued). "Autoantibodies against DSG3 have been found in skin keratinocytes from patients with pemphigus vulgaris." (PMID 23737966, 2013). "The appearance of a 60 kD fragment of desmoglein-3 occurs in vitro in keratinocytes treated with patient sera with pemphigus vulgaris." (PMID 22312325, 2012). "The importance of Dsg3 in cell–cell adhesion is highlighted by the autoimmune blistering disease pemphigus vulgaris (PV), where Dsg3 is the characterised autoantigen and a direct target of autoimmune antibodies." (PMID 22796473, 2012). "Pemphigus vulgaris antigen (also known as desmoglein 3 – DSG3) is one of the components of desmosome." (PMID 19997107, 2010). "In pemphigus vulgaris (PV), IgG autoantibodies against the ectodomain of desmoglein 3 (Dsg3) have been shown to be directly responsible for the loss of keratinocyteadhesion." (PMID 20671975, 2010). "Pemphigus vulgaris (PV) is a blistering autoimmune disease of the epidermis, characterized by IgG autoantibodies mainly against the desmosomal adhesion proteins, especially desmoglein-3 (Dsg3) and desmoglein-1 (Dsg1)." (PMID 39450168, 2024). "In two patients, an elevated DSG3 titer was found suspicious for pemphigus vulgaris." (PMID 38803350, 2024). "Pemphigus vulgaris (PV) is a chronic, potentially lethal autoimmune mucocutaneous bullous disease mediated by essentially IgG autoantibodies directed against desmogleins 1 and 3 (Dsg1 and Dsg3), cadherin-type cell–cell adhesion molecules present in desmosomes." (PMID 37511259, 2023). "Pemphigus vulgaris (PV) is an acquired autoimmune blistering disease characterized by the production of autoantibodies targeting desmosomal cadherins, primarily desmoglein 1 and desmoglein 3, leading to acantholysis." (PMID 37529044, 2023). "In one study, more anti-DSG3 antibodies undergoing somatic hypermutation were detected in patients with pemphigus vulgaris after diagnosis compared to before disease onset, and these antibodies exhibited increased binding affinity for DSG3 and induced better dissociation of keratinocytes." (PMID 37138879, 2023). "Furthermore, we examined the peripheral blood mononuclear cell (PBMC) analyses of 17 pemphigus vulgaris patients to identify subtypes of Dsg3-specific B cells related to the prognosis of rituximab treatment." (PMID 35983042, 2022). "Anti-DSG3 antibody generated without pathogenic activity of pemphigus vulgaris showed high antibody-dependent cell cytotoxicity (ADCC) against DSG3-expressing lung SCC." (PMID 35251162, 2022). "In pemphigus vulgaris patients, the frequency of IL-1β-expressing circulating Dsg1/Dsg3-specific B cells was significantly higher at baseline compared to healthy individuals and decreased to healthy control levels when in remission following rituximab treatment." (PMID 34068035, 2021). "Ellebrecht and colleagues have shown that Dsg3-CAAR-T cells could be used to specifically target Dsg3-specific B cells for the treatment of pemphigus vulgaris." (PMID 34068035, 2021). "Pathogenic epitopes of Dsg3 are also different between PNP and pemphigus vulgaris." (PMID 31214197, 2019). "Usually, in pemphigus vulgaris a mucosal-dominant phenotype (m-PV) is paralleled by autoantibodies against Dsg3 whereas epidermal involvement in PV (mc-PV) is in addition associated with formation of autoantibodies against Dsg1 which can also be found in pemphigus foliaceus (PF)." (PMID 31178865, 2019). "In addition, anti-Dsg3 antibody from PNP sera reacts with all five extracellular (EC) subdomains of human Dsg3, whereas anti-Dsg3 antibody from pemphigus vulgaris sera mainly binds to EC1 and EC2 domains." (PMID 31214197, 2019). "Additionally, pathogenic antibodies produced in the autoimmune epidermal blistering disease, pemphigus vulgaris, have been shown to alter intracellular signaling pathways upon binding to the extracellular domain of desmoglein-3 (DSG-3)." (PMID 29949915, 2018).
pemphigus vulgaris (continued). "Such an approach has demonstrated exciting results in vitro and in vivo in the case of CAAR T cells redirected against desmogelin-3 (DSG3) as a therapeutic approach for pemphigus vulgaris where B cells secrete autoantibodies against DSG3, which is an antigen expressed in the skin and mucosa." (PMID 29459866, 2018). "In pemphigus foliaceus, the antigenic target is desmoglein 1 (Dsg1), which is expressed at high concentrations in the superficial layers of the epidermis; in pemphigus vulgaris, the mucosal-dominant type antibodies target desmoglein 3 (Dsg3) in basal and parabasal layers of the skin." (PMID 29483905, 2018). "In contrast, pemphigus vulgaris (PV) patients may exhibit anti-DSG3 or anti-DSG3 and anti-DSG1 autoAb, known to specify the suprabasal blistering of mucous membranes or a mucocutaneous form, respectively [reviewed in Ref." (PMID 28928733, 2017). "Anti-Dsg-3 antibody in pemphigus vulgaris was also IgG4-predominant." (PMID 26018403, 2015). "It is worth noting that former diseases are T-helper-1 mediated autoimmune conditions, while pemphigus vulgaris is suggested to be a T-helper-2 type autoimmune disorder where autoreactive T-helper-2 cells to Dsg3 render B cells to secret Dsg3-specific antibodies." (PMID 24900992, 2014). "Furthermore, PKP3 binds in vivo to several other primary pemphigus vulgaris autoantigens including DSG3, DSG1, DSC1, and DSC3." (PMID 24988487, 2014). "Upon recognition of the Dsg3 in the recipient, the transferred Dsg3-specific lymphocytes induced lesions typical for pemphigus vulgaris: deposition of autoantibodies in the epidermis of the oral mucosa in a chicken-wire staining pattern and blistering within the basal epithelial layers." (PMID 24278779, 2013). "In pemphigus vulgaris (PV), autoantibodies (IgG) are generated against Dsg3, or both Dsg3 and Dsg1." (PMID 23226536, 2012). "Pemphigus vulgaris (PV) is an acquired autoimmune blistering disorder in which greater than 80% of active patients produce autoantibodies to the desmosomal protein desmogelin 3 (Dsg3)." (PMID 18564435, 2008). "As there are pathogenic DSG3 autoantibodies in pemphigus vulgaris and it might exhibit similar aspects of disease development and pathogenesis as AC, we performed in vitro cleavage assays utilizing DSG3, which is not expressed in cardiomyocytes." (PMID 37450050, 2023). "Pemphigus vulgaris (PV) is a very rare chronic bullous disease (1:1,000,000) which typically occurs in patients aged between 45 and 65 years, and it is characterized by the formation of autoantibodies, mainly of the IgG class, directed against desmoglein-1 and desmoglein-3 (Dsg1 and Dsg3 protein)." (PMID 37371152, 2023). "Pemphigus vulgaris (PV) is the most common subtype of a group of rare autoimmune blistering disorders (AIBD) in which autoantibodies primarily directed against the cell-cell adhesion molecules desmoglein 3 (Dsg3) and desmoglein 1 (Dsg1) lead to characteristic epidermal blistering." (PMID 36703956, 2022). "Furthermore, DRB1*14/04:06 may be able to present both Dsg1 and Dsg3 peptides, which may be the reason for antibodies against both antigens in pemphigus vulgaris with muco-cutaneous clinical phenotype." (PMID 33584677, 2020). "Autoantibodies targeting Dsg3 are found during the mucosal-dominant phase in pemphigus vulgaris (mPV) which is frequently followed by a mucocutaneous phase (mcPV) with additional epidermal blistering and characterized by the presence of both anti-Dsg3 and anti-Dsg1 antibodies." (PMID 29449846, 2018). "Finally, antibodies against DSG1 and DSG3 have been identified in pemphigus vulgaris or foliaceus." (PMID 27669234, 2016). "Dsg3 CAAR T cells, representing the first cellular immunotherapy for pemphigus vulgaris (PV), are currently under investigation in a Phase 1 trial for patients with mucosal-dominant PV." (PMID 39821376, 2025).
pemphigus vulgaris (continued). "For example, in the autoimmune disease pemphigus vulgaris, autoantibodies against desmoglein (DSG) protein 3 have been reported to lose reactivity to DSG3 when reverted to germline." (PMID 34479638, 2021). "In two patients, an elevated DSG3 titer was found, suspicious for pemphigus vulgaris although all other tests were negative including KBA." (PMID 38803350, 2024). "In pemphigus vulgaris, an antibody-mediated autoimmune blistering skin disease, CAAR T cells expressing the disease autoantigen desmoglein 3 was able to eliminate desmoglein 3-specific B cells in a mouse model even in the presence of circulating autoantibodies and without off-target toxicity." (PMID 36405681, 2022). "In our study, two patients presented anti-Dsg3-Abs without any clinical signs of pemphigus vulgaris." (PMID 23781320, 2013). "In the absence of flotillins, desmoglein-3 shows an altered localisation pattern in the cell-cell junctions of keratinocytes, which is highly similar to the localisation observed upon treatment with pemphigus vulgaris autoantibodies." (PMID 27346727, 2016). "However, none of the tested samples induced the internalization of Dsg3 when incubated with HaCaT cells, as opposed to IgG from a pemphigus vulgaris patient." (PMID 25971981, 2015). "The finding of hyperprolactinaemia in pemphigus vulgaris has been replicated in several studies in up to 22% of patients, although a correlation between serum PRL and desmoglein 3 and 1 antibodies was not identified." (PMID 39000207, 2024).